BRCA1 (BRCA1 DNA repair associated)
Diseases named in the same sentence as BRCA1 in open-access papers (continued):
Sharing a sentence is not in itself a finding about the gene and the disease.
breast cancer (continued). "Using the exome-sequencing method, we analyzed the genomes of blood cells in a typical BRCA1+ breast cancer family with an exon 13-duplicated founder mutation, including six breast cancer-affected and two breast cancer unaffected members." (PMID 24884718, 2014). "In summary, our DNAme signature derived from blood cells from BRCA1 carriers is able to predict breast cancer risk and death years in advance of diagnosis albeit with a modest AUC." (PMID 25067956, 2014). "Germline mutations in the breast cancer susceptibility gene, BRCA1 confer an estimated 60–85% and 40–60% lifetime risk of developing breast and ovarian cancer respectively by the age of 70." (PMID 24695549, 2014). "Women who carry pathogenic mutations in BRCA1 or BRCA2 have markedly increased risks of developing breast cancer." (PMID 25919761, 2014). "It is very different from the BRCA1 gene, for example, when one mutation is able to cause a breast cancer." (PMID 25415204, 2014). "Many common breast cancer susceptibility alleles identified through population-based genome-wide association studies (GWASs) have also been associated with breast cancer risk in BRCA1 and BRCA2 carriers." (PMID 25919761, 2014). "Although the BRCA1-3’UTR-variant has now been shown to predict a significant increased risk of breast cancer risk in three independent well-characterized cohorts, it is notable that this variant has not been reported from GWAS analyses." (PMID 24915755, 2014). "The current study provides evidence that genomic patterns resembling BRCA1- or BRCA2-mutated breast cancers can identify breast cancer patients with TN as well as ER-positive, HER2-negative tumors that are sensitive to intensified, DSB-inducing chemotherapy." (PMID 24887359, 2014). "Germline mutations of BRCA1 predispose to breast cancer and are characteristic of the hereditary form of this tumor." (PMID 24475217, 2014). "Regardless of specific populations and ethnic groups, recurrent BRCA1/2 mutations are rarely detected in hereditary breast cancer." (PMID 24884479, 2014). "Breast cancer susceptibility genes 1 and 2 (BRCA1/2) are known as tumor suppressor genes playing critical roles in DNA repair, cell cycle checkpoint control, and in maintenance of the genomic stability." (PMID 24775809, 2014). "Particularly, BRCA1-mutated basal-like breast cancers are believed to arise from the luminal progenitors." (PMID 25216750, 2014). "Hypermethylated E2F transcription factor 1 (E2F1) motif is a key regulatory element for the DNMT1 gene in BRCA1-mutated breast cancer." (PMID 24502362, 2014). "Breast cancer susceptibility gene 1 (BRCA1) is the most well-known gene linked to breast cancer risk." (PMID 25228385, 2014). "Based on the results above, we further explored the relationship between -132 site methylation and PEMT expression in BRCA1-mutated breast cancer specimens." (PMID 24675476, 2014). "Approximately half of these early breast cancers proved to emerge from germ-line mutations within the BRCA1 gene, which hamper the expression or functions of its protein." (PMID 24586743, 2014). "The BRCA1 A1708E founder mutation accounts for 1.3% of unselected breast cancers and 1% of unselected ovarian cancers in Bogota." (PMID 24742220, 2014). "Family history of breast cancer, early age at diagnosis, characteristics of the first primary (for example lobular histology and stage) and mutations in specific genes, including BRCA1, BRCA2 and CHEK2, are considered as risk factors." (PMID 25277819, 2014). "For example, mutations in BRCA1 (breast cancer 1, early onset) and BRCA2 (breast cancer 2, early onset) are important risk factors for PC." (PMID 25183411, 2014). "In fact, Poly-ADP-ribose polymerase 1 (PARP1), which plays a signaling role in the DNA Base Excision Repair pathway (BER), is critical for viability of familial breast cancer cells deficient in HR proteins BRCA1 and BRCA2." (PMID 25185513, 2014).
breast cancer (continued). "Among 35 selected cases with a family history and/or bilateral breast cancers, the BRCA1/2 mutation prevalence was 25.7% (9/35)." (PMID 24961674, 2014). "Here we have provided several novel lines of evidence indicating that DNAme profiles obtained in cells from women with a BRCA1 mutation have the potential to indicate future breast cancer development (and death) many years in advance of diagnosis." (PMID 25067956, 2014). "In line with this, clinicopathological data indicated that the hypermethylated E2F1 motif was significantly associated with histological grade, lymph node, Ki67 and E-cadherin status in BRCA1-mutated breast cancer." (PMID 24502362, 2014). "A recent study demonstrates that BRCA1 mutations in breast cancer drive oxidative stress and glycolytic transformation of the tumor." (PMID 25136623, 2014). "Overall, 15 breast cancer susceptibility variants were associated with ER-negative breast cancer in BRCA1 carriers and 8 variants in BRCA2 carriers at P <0.05." (PMID 25919761, 2014). "Taken together, our findings document the role of XRCC4 in non-BRCA1/2 breast cancer predisposition and reveal its underlying biological mechanism of action." (PMID 25360583, 2014). "Recent studies have found direct associations between specific SNPs and breast cancer in BRCA1/2 mutation carriers." (PMID 25274085, 2014). "In conclusion, we combined epidemiologic and experimental studies to establish a role for XRCC4 in the predisposition to non-BRCA1/2 breast cancer in a Chinese population." (PMID 25360583, 2014). "Regarding germline mutations, BRCA1/2 mutations are the most common, accounting for up to 40% of familial breast cancer." (PMID 25436920, 2014). "A previously unreported SNP at 2p13.2 was associated with HER2-positive breast cancer in BRCA1 carriers." (PMID 25919761, 2014). "Multivariate Cox regression analysis indicated that lymph node metastasis was an independent prognostic factor for predicting the overall survival of BRCA1-mutated breast cancer patients (P = 0.038)." (PMID 24502362, 2014). "For example, an insertion/deletion mutation in intron 24 (3′ UTR) of BRCA1 gene was found in one of the families with five breast cancer patients." (PMID 25034901, 2014). "One component within the network, HMMR gene, which encodes a centrosome subunit, was discovered to be associated with the breast cancer-associated gene BRCA1 and with a higher risk of breast cancer." (PMID 24995123, 2014). "Women with a strong family history of cancer who possess a harmful BRCA1 or BRCA2 allele are at high risk for developing breast cancer within their lifetime (80% and 60%, respectively)." (PMID 25011685, 2014). "RAD51 (RAD50 forms MRE11-NSB1-RAD50 complex) also interacts with breast cancer susceptibility genes 1 and 2 (BRCA1/BRCA2)." (PMID 24752797, 2014). "Poly (ADP-ribose) polymerase (PARP), EGFR, and mTOR inhibitors are among the therapeutic agents being studied in patients with TNBC and BRCA1-associated breast cancers." (PMID 24507701, 2014). "In this study, we report that the first-promoter-specific transcript 1 is the major PEMT mRNA species in human breast tissues, and that methylation of the -132 site is a key regulatory element for PEMT transcription in BRCA1-mutated breast cancer." (PMID 24675476, 2014). "Our study identified multiple recurrent germline and somatic mutations in the genomes of blood cells, highlighting that BRCA1+ can cause genome instability in both breast cancer cells and non-breast cancer cells." (PMID 24884718, 2014). "The potential link between breast cancer and childhood cancer is of great interest, given past reports of increased rates of childhood cancer in families carrying a BRCA1 or BRCA2 mutation." (PMID 24799902, 2014). "In a large analysis including 3,345 patients who were aged ≤50 years at the time of breast cancer diagnosis, 7% of patients had a BRCA1 mutation." (PMID 25436920, 2014).
breast cancer (continued). "Stratification by BRCA1/BRCA2 mutation status showed that the occurrence of contralateral breast cancer was eight fold higher among mutation carriers compared with non-carriers." (PMID 24834114, 2014). "Controlling for other disease variables in a multi-variant model, patients with Stage IV disease were three-fold more likely to have the BRCA1-3’UTR-variant compared to all other stages of breast cancer (p = 0.055, OR 2.76, 95% CI 1.0-7.8)." (PMID 24915755, 2014). "Interest in platinum-based therapies was renewed with the observation that BRCA1 deficient cell lines have a higher sensitivity to DNA crosslinking agents, such as cisplatin, compared with other breast cancer cell lines." (PMID 24527094, 2014). "Women carrying germline mutations in the BRCA1 gene have a 50%–80% lifetime risk of developing breast cancer and a 20%–40% lifetime risk of developing ovarian cancer." (PMID 24704793, 2014). "A DNAme signature derived from BRCA1 carriers is able to predict breast cancer risk and death years in advance of diagnosis." (PMID 25067956, 2014). "In a separate study, PTEN loss was found to be a predictor of BRCA1 germ-line mutations in women with early onset breast cancer." (PMID 24830350, 2014). "This concept is supported by the CGH findings in mouse models of BRCA1-associated breast cancer, showing a highly similar pattern of CNAs in different BRCA1-deficient mouse mammary tumours, which was highly reproducible over different studies." (PMID 25083859, 2014). "The BRCA1 tumor suppressor, germline mutations in which predispose to ovarian and breast cancer, localizes to APBs." (PMID 24709898, 2014). "This study provides new insights into the causes and prognosis of PEMT inactivation in BRCA1-mutated breast cancer." (PMID 24675476, 2014). "Methylation of the BRCA1 promoter and associated loss of expression of the gene have been reported in approximately 25% of breast cancers, with the frequency in TNBC reported to be as high as 31%." (PMID 25475740, 2014). "Although there was no significant change in the expression of PCAF and HLCS, the expression level of GCN5 was reduced, and EHMT-1 was increased in BRCA1-mutated breast cancer (P < 0.05)." (PMID 24675476, 2014). "In summary, our investigations have provided information of clinical utility for 18 of 19 BRCA1 or BRCA2 variants identified by clinical germline testing of breast cancer patients." (PMID 24489791, 2014). "A variant in the 3’UTR of BRCA1 is functional, leading to decreased BRCA1 expression, modest increased breast cancer risk, and most importantly, presentation with stage IV breast cancer, likely due to aggressive tumor biology." (PMID 24915755, 2014). "Another important role for SIRT1 in cancer is its suppression of the apoptosis inhibitor survivin in breast cancer susceptibility gene 1 (BRCA1)-associated breast cancers." (PMID 25486244, 2014). "The current study identified XRCC4 as a non-BRCA1/2 breast cancer susceptibility gene in the Chinese population." (PMID 25360583, 2014). "In this study, we have compared the genomic alterations linked to a defect in BRCA1 within one breast cancer subtype, the TNBC." (PMID 25416589, 2014). "A number of these histopathological features have been incorporated into prediction models or have been proposed as selection criteria for prioritizing testing of breast cancer patients for BRCA1 and BRCA2 mutations." (PMID 25857409, 2014). "The principal genes involved in the risk of breast cancer are BRCA1 and BRCA2, which account for about 20-50% of all HBC cases." (PMID 24986639, 2014). "In this study, the prevalence of BRCA1 mutations in 106 familial Greek ovarian cancer patients who had a strong family history of ovarian cancer or metachronous breast cancer." (PMID 25051360, 2014).
breast cancer (continued). "The BRCA1 p.Ser36Tyr variant was found 17 times in the MASTOS breast cancer case-control series, with an overall frequency of 1.2% in the breast cancer cases group (n = 13) and 0.34% (n = 4) in the unaffected controls." (PMID 24695549, 2014). "Our study identified epigenetic-mediated DNMT1 transcriptional repression, which involved the hypermethylated E2F1 motif-mediated loss of active histone modification H3K9ac and transcription factor E2F1 enrichment in BRCA1-mutated breast cancer." (PMID 24502362, 2014). "BRCA1-mutated basal-like breast cancers are believed to arise from a developmental stage of the mammary epithelial cell, which is different from the primitive stem cell, named the luminal progenitors." (PMID 25216750, 2014). "The BRCA1-3’UTR-variant (TG or TT) also associated with a modest increased risk for developing breast cancer in the West-Irish cohort (OR = 1.4, 95% CI 1.1-1.8, p = 0.033)." (PMID 24915755, 2014). "Regression analyses of all breast cancer cases evaluating the contributory role of age, menopausal status, tumor grade, stage and ER/PR status in predicting the BRCA1-3’UTR-variant was significant only for stage." (PMID 24915755, 2014). "We next evaluated the association of the BRCA1-3’UTR-variant across the various breast cancer subtypes." (PMID 24915755, 2014). "Two major breast cancer susceptibility genes are BRCA1 and BRCA2, located on chromosomes 17 and 13, respectively and both perform function as tumor suppressor genes." (PMID 24711893, 2014). "BRCA1-associated breast cancers often occur in younger women, and these tumors are high grade and lack estrogen receptors (ERs), and are often triple-negative and, as such, harder to treat." (PMID 25293656, 2014). "For example, the major driver genes BRCA1/2 for breast cancer are frequently (10∼20%) mutated in the cancer cells of the patients with ovarian tumors." (PMID 25390899, 2014). "For breast cancer patients with BRCA1 mutation, single-agent cisplatin NAT can achieve an extremely high pCR rate of 83%." (PMID 25247558, 2014). "Activation of the P-glycoprotein drug efflux transporter was also shown to confer resistance to the PARP inhibitor olaparib in a BRCA1-deficient mouse mammary tumor." (PMID 25026298, 2014). "Tumor gene expression studies of BRCA-mutations in malignant canine mammary tumors have shown varied results with under-expression of BRCA1 in malignant, as well as over-expression of BRCA2 in metastatic tumors." (PMID 24641873, 2014). "Here, we have identified an additional reliable antigen, CD338/ABCG2, that can be used to refine the sorting of the luminal progenitor subpopulations of BRCA1-mutated breast cancer cells." (PMID 25216750, 2014). "These analyses demonstrated that, despite the lack of an association between some susceptibility variants and overall breast cancer risk for BRCA1 or BRCA2 carriers, residual associations exist with specific disease subtypes." (PMID 25919761, 2014). "Among these preventive options, bilateral mastectomy, although invasive, reduces approximately 90% the risk of breast cancer in women with BRCA1/2 mutations." (PMID 24591761, 2014). "Evidence for MRE11A rests primarily on the observation of two mutations in the gene from a series of eight non-BRCA1/2 breast cancer families with tumors that showed loss of all three MRN proteins." (PMID 24894818, 2014). "Particularly, we have identified a gain in the 17q25.3 region that is highly recurrent in BRCA1-mutated breast cancer." (PMID 25416589, 2014). "Poly (ADP-ribose) polymerase 1 (PARP1) inhibitor (PARPi)-mediated therapy is a promising approach for familial breast cancers caused by mutations of breast cancer-associated gene-1 and -2 (BRCA1/2), yet drug resistance frequently occurs during the treatment." (PMID 24962108, 2014). "Among the established risk factors for breast cancer are germline mutations in two highly penetrant genes: BRCA1 and BRCA2." (PMID 25409685, 2014).
breast cancer (continued). "If we remove the 35 cases with family history and/or bilateral breast cancers from the analysis, a total of 15 (24.6%) BRCA1/2 mutations were identified in the remaining 61 patients of unselected triple-negative breast cancer." (PMID 24961674, 2014). "The GPS score had a protective effect in the whole BRCA1 population and in the ovulating strata (RH 0.76/0.58, p > 0.015), and was associated to a higher hazard of breast cancer in the BRCA2 whole population (RH = 1.33, p = 0.035)." (PMID 25274085, 2014). "Mutations in the BRCA genes are responsible for the increased risk of breast cancer, specifically 59–87 and 38–80% for BRCA1 and BRCA2 mutations respectively." (PMID 24795863, 2014). "Women with BRCA1 mutations typically develop breast cancer at an earlier age than BRCA2-related and sporadic breast cancers." (PMID 24579064, 2014). "The estimated lifetime risk of developing breast cancer for women with BRCA1 and BRCA2 mutations is 40% to 85%." (PMID 25184114, 2014). "Elevated c-Myc expression leads to a poor prognosis in sporadic breast cancer patients that are BRCA1-deficient." (PMID 25051360, 2014). "The two major contributors to hereditary breast cancer are the breast cancer susceptibility gene 1 (BRCA1) and BRCA2." (PMID 24961674, 2014). "Further studies will be carried out to address the functional significance and clinical relevance of the 17q25.3 gain and gene over-expression in BRCA1-mutated breast cancer, such as the prediction of the response to alkylating agent or platinum-based therapy." (PMID 25416589, 2014). "This study examines the frequency of BRCA1/2 defects and elevated scores across breast cancer subtypes, and examines the association of the HRD-LOH, HRD-TAI, and HRD-LST scores with BRCA1/2 deficiency in breast tumors." (PMID 25475740, 2014). "The risk of developing breast or ovarian cancer in individuals with certain cancer-associated BRCA1/BRCA2 alleles is 60-80% for breast cancer and 20-40% for ovarian cancer." (PMID 25051360, 2014). "It appeared that some sporadic breast cancers had aCGH patterns that resembled BRCA1-mutated breast cancers." (PMID 24887359, 2014). "In the univariate analyses, BRCA1-positive status was associated with decreased risk of distant recurrence (HR, 0.228; 95% Cl, 0.052–0.997; P<0.049) and breast cancer-specific mortality (HR, 0.209; 95% Cl, 0.048–0.902; P<0.036)." (PMID 24348864, 2014). "A total of 244 breast cancer patients were tested for BRCA1 and BRCA2 mutations using a combination of laboratory techniques." (PMID 24742220, 2014). "Based on the results above, we next explored the relationship between E2F1 motif methylation and DNMT1 expression in a large number of BRCA1-mutated breast cancer specimens." (PMID 24502362, 2014). "Bioinformatics analysis, using PolyPhen and Align-GVGD yielded contradictory predictions regarding the pathogenicity of the p.Ser36Tyr BRCA1 variant, identified in 4 Cypriot families and in 13 cases of sporadic breast cancer." (PMID 24695549, 2014). "In sporadic breast cancer, BRCA1 mutations are rare, but reduced expression or aberrant subcellular localization of BRCA1 is common among young African-American women with TNBC." (PMID 23873416, 2014). "BRCA1, a tumor suppressor gene that is frequently mutated in breast cancer, was chosen for further investigation." (PMID 25107276, 2014). "These TNBCs resemble breast cancers of BRCA1-mutation carriers not only with respect to their level of genomic instability but also in terms of their gene expression patterns and their lack of expression of hormone receptors." (PMID 25083859, 2014). "As in the BRCA1 population, there was only one case of breast cancer after risk reducing mastectomy (out of 17 women operated)." (PMID 25274085, 2014). "It is known that hypoxia induces BRCA1 downregulation and that BRCA1-mutated breast carcinomas, which are enriched in HIF-1α expression, present aberrant expression of P-cadherin." (PMID 25269858, 2014).